MDM4 (MDM4 regulator of p53)
Diseases named in the same sentence as MDM4 in open-access papers (continued):
Sharing a sentence is not in itself a finding about the gene and the disease.
pulmonary fibrosis (8 papers, 2021 to 2025). Chronic progressive interstitial lung disorder characterized by the replacement of the lung tissue by connective tissue, leading to progressive dyspnea, respiratory failure, or right heart failure. "Genetic ablation of mouse Mdm4 in lung (myo)fibroblasts reverses persistent lung fibrosis associated with aging." (PMID 33688918, 2021). "Our studies provides evidence that mechanosensitive MDM4 is a molecular target with promising therapeutic potential against persistent lung fibrosis associated with aging." (PMID 35126134, 2021). "In this study, we evaluated the efficacy of XI-011, a small molecular inhibitor of MDM4, for treating lung fibrosis." (PMID 37284444, 2023). "To verify if XI-011 could reverse MDM4 effects in lung fibrosis, we harvested normal and fibrotic mouse lung tissues treated with or without XI-011." (PMID 37284444, 2023). "In this study, we sought to determine whether pharmacological inhibition of MDM4 could alleviate lung fibrosis." (PMID 37284444, 2023). "Mdm4 expression in bleomycin-treated mouse lungs was time dependent, with minimal expression at day 3 (acute lung injury), increasing expression at days 7 and 10 (lung inflammation), and highest expression at day 28 (lung fibrosis)." (PMID 33688918, 2021). "In this study, we found that mouse double minute 4 homolog (MDM4) is highly expressed in the fibrotic lesions of human IPF and experimental pulmonary fibrosis in aged mice." (PMID 33688918, 2021). "In this study, we observed that MDM4 is highly expressed in the fibrotic lesions of both human IPF and bleomycin-induced experimental lung fibrosis in aged mice." (PMID 33688918, 2021). "MDM4 is highly expressed in the fibrotic lesions of human IPF and experimental pulmonary fibrosis in aged mice." (PMID 35126134, 2021). "High levels of MDM4 were expressed in the fibrotic lesions of human IPF and experimental lung fibrosis in aged mice." (PMID 33688918, 2021).
pulmonary fibrosis (continued). "Destiffening of the fibrotic ECM by targeting nonenzymatic glycation cross-linking or genetic ablation of Mdm4 in collagen I–producing (myo)fibroblasts reverses persistent lung fibrosis in aged mice." (PMID 33688918, 2021). "The current study identifies mechanosensitive MDM4 as a novel molecular target in pulmonary fibrosis and highlights the therapeutic potential of targeting nonenzymatic AGE cross-linking to reverse persistent lung fibrosis associated with aging." (PMID 33688918, 2021).
sarcoma (8 papers, 2013 to 2024). A usually aggressive malignant neoplasm of the soft tissue or bone. "A previous study reported that IR-induced decreases in MDM4 expression in sarcoma cells occurred in a Chk2-dependent manner." (PMID 39273420, 2024). "As such, MDM4 protein expression in a cohort of 36 sarcoma samples of varying histopathology was determined through immunohistochemical analysis (IHC)." (PMID 26095524, 2015). "The majority of studies that have evaluated sarcoma MDM4 expression levels have done so through quantification of mRNA." (PMID 26095524, 2015). "Copy-number amplification of MDM2 and MDM4 has also been specifically reported in Ewing’s Sarcoma, and co-amplification of both have been observed in a sub-set of sarcomas." (PMID 24321497, 2013). "Indeed, MDM4 IHC analysis of our sarcoma cohort detected MDM4 protein expression (>10 positive cells) in 33.3% (12/36) of cases and was highly prevalent in well/de-differentiated liposarcomas and myxofibrosarcomas." (PMID 26095524, 2015). "Interestingly, well/de-differentiated liposarcomas and myxofibrosarcomas exhibited significantly higher levels of MDM4 protein expression compared to the rest of the sarcoma cohort (p < 0.0001)." (PMID 26095524, 2015).
triple-negative breast carcinoma (8 papers, 2016 to 2024). An invasive breast carcinoma which is negative for expression of estrogen receptor (ER), progesterone receptor (PR), and human epidermal growth factor receptor 2 (HER2). "This is further confirmed by yet another study wherein it is reported that another SNP rs34091, also located on the 3′UTR of MDM4, is also associated with an increased risk of triple negative breast cancer." (PMID 32823908, 2020). "In earlier studies with three GWAS of ER-negative breast cancer patients, including the TNBC group, it has been observed that rs4245739 in the 3′UTR region of MDM4, creating a novel site for miR-191, is specific to triple negative breast cancer patients." (PMID 32823908, 2020). "MDM4 has also been suggested to promote triple-negative breast cancer metastasis." (PMID 32802855, 2020). "MDM4, whose splicing was previously shown to be regulated by SRSF10, and affected by GPS167, may also be important for metastasis since its knockdown reduces circulating tumor cells in triple-negative breast cancer without affecting proliferation." (PMID 38753413, 2024).
lymphoma (7 papers, 2015 to 2025). A malignant (clonal) proliferation of B- lymphocytes or T- lymphocytes which involves the lymph nodes, bone marrow and/or extranodal sites.
breast tumor (6 papers, 2016 to 2024). "The expression of MDM4 gene is positively correlated with the expression of ERα in primary breast tumors." (PMID 33324444, 2020). "Noteworthy, MDM4 transcript levels are significantly reduced in breast tumors characterized by high mTOR levels." (PMID 28270148, 2017). "In the clinic, these protumorigenic functions of MDM4 are likely facilitated by the overexpression of the MDM4 gene, which occurs in approximately 20-55% of primary human breast tumors." (PMID 26909605, 2016). "In addition, we demonstrate that tumors of luminal A and luminal B molecular subtypes have the highest expression of MDM2 and MDM4 mRNA, in agreement with a prior study that observed that MDM4 protein expression is similarly elevated in luminal A/B breast tumors." (PMID 26909605, 2016). "The expression levels of MDM4, MDM2, YAP1, and YPEL3 in human breast tumor samples were investigated compared to normal samples using TNM plot analysis." (PMID 39345743, 2024). "Having demonstrated that ERα regulates MDM4 and MDM2 mRNA expression, and additionally, that MDM4 and MDM2 mRNA expression is specifically elevated in ERα-positive primary human breast tumors, we postulated that ERα transcriptionally regulates MDM4 and MDM2 genes." (PMID 26909605, 2016).
cervical cancer (6 papers, 2021 to 2025). A primary or metastatic malignant neoplasm involving the cervix. "MDM4 was confirmed as an oncogenic molecule in cervical cancer in previous studies." (PMID 38800376, 2024). "Based on these, we hypothesized that miR-875-5p inhibits the growth and metastasis of cervical carcinoma by targeting MDM4." (PMID 38800376, 2024).
cutaneous melanoma (6 papers, 2016 to 2024). A primary melanoma arising from atypical melanocytes in the skin. "The inhibition of MDM4 remains a “key therapeutic target in cutaneous melanoma”, potentially through alterations in the splicing landscape and resulting functional changes." (PMID 39273363, 2024). "We have investigated the transcriptional changes occurring in uveal and cutaneous melanoma cell lines upon depletion of MDMX (aka:MDM4)." (PMID 36139642, 2022).
hepatocellular carcinoma (6 papers, 2021 to 2025). A malignant tumor that arises from hepatocytes. "Interactions between SRF and ETS domain transcription factors have also been reported to be one of the mechanisms for the regulation of the transcription of the mouse double minute 4 protein (MDM 4) oncogene in hepatocellular carcinoma (HCC)." (PMID 32885587, 2021). "Additionally, another study listed in the TCGA’s database suggested that amplification of mouse double minute 4 (MDM4) is an important genetic change in the development of hepatocellular carcinoma (HCC), and a drug targeting this amplification has been undergoing clinical trials." (PMID 38890691, 2024).
neuroblastoma (6 papers, 2019 to 2024). Neuroblastoma (NB) is the most common solid, extracranial childhood tumor. "Likewise, SP141 has also been found to reduce the protein levels of both MDM2 and MDMX (MDM4) in neuroblastoma cells." (PMID 33291373, 2020).
pancreatic cancer (6 papers, 2017 to 2024).
bladder cancer (5 papers, 2014 to 2022). "To validate these observations in clinical settings, we next analyzed the messages of 20 paired patient tissues and found that MDM4 mRNA was significantly upregulated in bladder cancer tissues compared with their adjacent normal tissues (P = 0.01)." (PMID 35778656, 2022). "Taken together, our findings indicated the tumor suppressor functions of miR-1307-5p in bladder cancer and its anti-tumor effectors include MDM4 and the Hippo pathway." (PMID 35778656, 2022). "Collectively, the results indicated in in vitro, in vivo, and clinical settings that MDM4 is a direct downstream target of miR-1307-5p in bladder cancer." (PMID 35778656, 2022). "Our preliminary results indicate a putative role for the MDM4 gene in predicting local recurrence of bladder cancer." (PMID 25026175, 2014). "In conclusion, miR-1307-5p overexpression could suppress tumorigenesis of bladder cancer by inhibiting MDM4 and its downstream Hippo pathway in bladder cancer." (PMID 35778656, 2022). "In addition, we found that miR-1307-5p overexpression would suppress bladder cancer cell growth by inhibiting MDM4 and its downstream Hippo pathway." (PMID 35778656, 2022). "Indeed, a significant inverse correlation existed in bladder cancer tissues between the RNA levels of miR-1307-5p and MDM4, as evaluated by Spearman’s correlation test." (PMID 35778656, 2022). "We further found miR-1307-5p significantly inhibited the Hippo pathway via MDM4 in bladder cancer." (PMID 35778656, 2022).
endometrial cancer (5 papers, 2015 to 2022). Primary or metastatic malignant neoplasm involving the endometrium (mucous membrane that lines the endometrial cavity). "Regarding fertility, MDM4 variants are associated with the susceptibility of ovarian and endometrial cancer." (PMID 32408659, 2020). "In this study, we assessed the impact of MDM4 SNP34091 status on the risk of ovarian and endometrial cancer in large hospital-based sample sets." (PMID 26867771, 2016). "In this study, we examined the association between the MDM4 SNP34091 status and ovarian- and endometrial cancer risk applying a case-control design." (PMID 26867771, 2016). "Notably, among cell lines registered in Cancer Cell Line Encyclopedia (CCLE–Broad Institute), we found a lower average MDM4 expression level among ovarian—than endometrial cancer cells." (PMID 26867771, 2016). "Regarding the present analyses, MDM4 SNP34091 status was successfully genotyped in 1385 ovarian and 1404 endometrial cancers cases." (PMID 26867771, 2016). "In contrast, we found no synergistic effects between MDM4 SNP34091 and MDM2 SNPs with respect to endometrial cancer risk (data not shown)." (PMID 26867771, 2016). "Since we found an effect of MDM4 SNP34901 in ovarian—but not endometrial cancer, we mined the publically available data set from the Broad-Novartis Cancer Cell Line Encyclopedia (CCLE–Broad Institute; www." (PMID 26867771, 2016). "We thus propose that future studies on the role of additional multi-cancer regions, such as 1q32/MDM4, 4q24/TET2, 8q24, 10p12/MLT10, 14q24/RAD51B8 or 19q13/MERIT40, are worthwhile endeavours for cancers that are relatively understudied, including endometrial cancer." (PMID 25487306, 2015).
lung adenocarcinoma (5 papers, 2014 to 2024). A carcinoma that arises from the lung and is characterized by the presence of malignant glandular epithelial cells. "Stratification analysis revealed that the effect of MDM4 SNPs was more pronounced in lung adenocarcinoma (LAC) subgroups." (PMID 27462918, 2017).
uveal melanoma (5 papers, 2018 to 2024). A melanoma derived from melanocytes of the uveal tract.
B-cell lymphomas (4 papers, 2009 to 2021).